IL1B (interleukin 1 beta)
Diseases named in the same sentence as IL1B in open-access papers (continued):
Sharing a sentence is not in itself a finding about the gene and the disease.
infection (continued). "Macrophages actively participate in inflammatory responses by releasing pro-inflammatory cytokines: TNF-α, IL-1β, and IL-6 as well as inflammatory cytokines such as NO and PGE2 and recruit additional immune cells to the site of infection or tissue injury." (PMID 35743169, 2022). "The mRNA levels of IL-1β, IL-6 and TNF-α were significantly higher in the brains and lungs of ISG15-/- mice as compared with those of WT mice at different time points post infection." (PMID 36315588, 2022). "Subsequently, the regulation of the immune response to infection adjusts the expression of inflammatory factors, including iNOS, COX-2, IL-6, IL-1β, and TNF-α." (PMID 35159514, 2022). "The transcription of IL-1β, TNF-a and TLR2 has been shown to increase after stimulation with D. nodosus in a single-cell-type infection model using ovine fibroblasts." (PMID 36496756, 2022). "Accumulating evidence suggests that IL-1β and TNF-α are typical pro-inflammatory cytokines that are rapidly increased when tissue injury or infection." (PMID 36118767, 2022). "The naïve infection control group showed the highest levels of TNF-α, IL-6, IFN-γ, and IL-1β cytokines in airway BALF and lung samples at 5 days after infection." (PMID 36146461, 2022). "In infection-triggered ME/CFS, IL-1b release is inversely correlated with sCD26 expression, while the expression level of sCD26 has been linked to health-related quality of life." (PMID 36189286, 2022). "IL-1β is a chemoattractant for neutrophils in zebrafish, and TNF-α is one of the early immune genes expressed at an early stage of infection in fish and has a key role in regulating inflammation." (PMID 35563763, 2022). "At 4 h post-infection, PA14 and B12 infected cells produced significantly higher levels (39 and 54 pg ul−1, respectively) of IL-1β than PAO1 and D1 infected cells (5 and 3 pg ul−1, respectively) (One-way ANOVA, Tukey post-hoc, P<0.05)." (PMID 35275806, 2022). "Protein and mRNA levels of IL-6 and IL-1β were significantly reduced in ASO MIR99AHG treated BMDMs compared to controls following IL-4/IL-13 stimulation and Mtb HN878 infection." (PMID 35895506, 2022). "Collectively, ASFV-ΔH240R infection induced the activation of caspase 1 and the release of IL-1β from the ASFV-ΔH240R-infected PAMs, suggesting that the inflammasome is activated upon ASFV-ΔH240R infection." (PMID 36326277, 2022). "In the early stage of infection, a variety of inflammatory cells are recruited and activated to release large amounts of inflammatory cytokines and chemokines, such as TNF-α and IL-1β, which are rapidly secreted and reach to the peak within a few hours." (PMID 35197984, 2022). "We noted moderately elevated levels of IL-1β, TNF-α, and IFN-γ in C3ar-/- lungs at 6 days post-infection." (PMID 36174103, 2022). "Previous data demonstrated that infection with attenuated IBV upregulated the expression of proinflammatory cytokines, including IL-1β, IL-6, and IFN-γ." (PMID 35392927, 2022). "A cascade of biomolecular events occurs in an intricate network after exposure infection of SARS-COV-2 including the production of interleukins 1β, 6, 10 (IL-1β, IL-6, IL-10, MCP-1), and tumor necrosis factor-α (TNF-α)." (PMID 34463916, 2022). "In one study using live bacteria, infection of PMNs with methicillin resistant S. aureus resulted in MitROS production that also triggered NET formation and IL-1β production within four hours of infection." (PMID 36374941, 2022). "Correspondingly, BCG ΔPPE36 infection led to the increased inflammatory cytokines (TNF-α, IL-6, and IL-1β) and the reduced lung bacterial loads." (PMID 35237255, 2022). "So, our study represents the first report on the effects of moringa leaves dietary inclusion on the transcriptomic profile of inflammatory mediator genes, such as IL-1β, IL-8, and IFN-γ under normal health and infection conditions." (PMID 35812877, 2022).
infection (continued). "During the latent and reactivation phase of MDV infection (7–28 dpi), the transcriptional upregulation of chicken IL-1β, IL6, IL-8L1 IFN-γ and PML in the spleen and bursa induced by MDV/RB1B infection was overall stronger than that of MDV/CVI988." (PMID 36680047, 2022). "During infection of THP-1 cells in which WASp was depleted via shRNA-mediated knockdown, IL-1β secretion and bacterial replication was increased compared to control cells with unperturbed levels of WASp." (PMID 35801644, 2022). "Moreover, with the exception of il1b, signature genes of Cxcl10+ and Saa3+ monocytes were also upregulated in Ly6Chi monocytes from L. monocytogenes-infected mice, indicating a broad repertoire of putative new Ly6Chi monocyte subsets during this type of infection." (PMID 36010615, 2022). "IL-1β and IFN-γ cytokines are able to protect the intestine from infection by triggering an immune response and preventing the spread of pathogens, respectively." (PMID 35647094, 2022). "For example, exposure to cytokines such as TNF-α, IL-1β, IFN-γ and GM-CSF, can drive neutrophil activation as well as amplify neutrophil recruitment to the site of infection." (PMID 36203565, 2022). "In general, the BCGΔRS01790 infection group exhibited significantly higher serum levels of IFN-γ, TNF-α, and IL-1β than WT BCG and cBCGΔRS01790::RS01790 groups before 8 dpi." (PMID 35281073, 2022). "ELISA assay revealed consistent results with the qRT-PCR assay, suggesting that dTHP1 cells secreted large amounts of proinflammatory cytokines (IL-6, IL-1β, and TNF-α) and chemokine MCP-1 into the supernatant during the infection process (p < 0.05)." (PMID 35359716, 2022). "During the inflammatory period, macrophages secrete pro-inflammatory factors (IL-1β, TNF-α, IL-6, etc.)and anti-inflammatory factors (IL-10) to clear the necrotic tissue and prevent infection at the wound site." (PMID 35877710, 2022). "Th1 cytokines (IL-1β, IL-2, IL-12p70, IFN-γ and TNF-α), Th2 cytokine (IL-4), as well as Th17 cytokine (IL-17A) showed decreasing trend by infection intensity." (PMID 36083861, 2022). "The ELISA results demonstrated that PRV-infection induced a high level of IFN-α and IFN-β, but a weak release of IL-1β after PRV infection for 2 d and 5 d in pigs." (PMID 35458442, 2022). "In the primary infection, the mRNA levels of cytokines and chemokines including RANTES, IFN-α, MIP-1-α, IFN-γ, IL-6, IP-10, TNF-α, and IL-1-β were increased in the nasal mucosa and lung, except IL-1-β, which was not increased in the lung." (PMID 35893674, 2022). "The plasma levels of IL-6, IL-1β, and TNF-α were higher in the untreated group than in the mock group on days 1, 3, and 5 post-infection." (PMID 36569095, 2022). "Cytokines can be proinflammatory, such as IL-1β, IL-6, and TNF-α, and alert other immune cells to the infection, or they can be anti-inflammatory." (PMID 36558734, 2022). "CRP is increased in response to IL-6, IL-1β and TNF-α activation during infection and systemic inflammation." (PMID 35958594, 2022). "The infection with HN878 is known to induce a different inflammatory pattern (e.g., strong production of IL-1β and type 1 IFN) and protective mechanisms (e.g., IL-17 and IL-22 production) compared to H37Rv." (PMID 35443177, 2022). "Mice in the CoHo-PBS group significantly reduced the mRNA expression levels of pro-inflammatory cytokines (IL-1β, IL-6, and TNF-α) compared with the SiHo-PBS group after infection." (PMID 35123452, 2022). "Some studies have suggested that IL-1β, TNF-α, IL-2, IFN-γ, and IL-6 were markedly upregulated in critical patients after infection with SARS-CoV-2 and thus can be used as biomarkers to determine the severity of disease in patients." (PMID 36069561, 2022).
infection (continued). "Although the protective role of inflammasome signaling and IL-1β release has been demonstrated against different pathogens, their uncontrolled activation might lead to enhanced tissue damage, along with unrestrained recruitment of immune cells to the site of infection." (PMID 35336937, 2022). "Various inflammatory cytokines such as TNF (TNF), some ILs (IL1α, IL1β), and chemokines (including CCL2, CCL4, CCL5, CXCL8) were significantly up-regulated under all observation points after YC-2020 infection." (PMID 36338035, 2022). "Of note, we demonstrated that si‐Hsf1 counteracted melatonin‐mediated suppressive effects on the levels of IL‐1β and TNF‐α in the serum and lung at 12 h post PmCQ2 infection." (PMID 35184395, 2022). "The results show a significant upregulated mRNA expression of TNF-α, IL-1β, IL-8 and CCL20 after infection with ETEC as compared to the control condition across both groups." (PMID 36145526, 2022). "In vitro, infection of Vero-E6 cells with SARS-CoV-2 induced senescence (SenTraGor), DNA damage (γ-H2AX) and increased cytokine (IL-1β, IL-6, CXCL8) and apolipoprotein B mRNA-editing (APOBEC) enzyme expression." (PMID 35086840, 2022). "Some inflammatory cytokines, including IL-1β, IL-6, IL-8, and TNF-α, were frequently measured during biomaterial-related infections." (PMID 35203495, 2022). "Infection performed in NOD-, LRR-, and pyrin domain-containing three (NLRP3) knockdown cells indicated that NLRP3 is essential for SVA-induced IL-1β secretion." (PMID 35254168, 2022). "First, SC were infected with ONNV at a multiplicity of infection (MOI) 1, 10−1, 10−2, and 10−3 or stimulated with the viral analog PIC 10 μg/mL, ATP 1 mM, TGF-β2 10 ng/mL, or the proinflammatory cytokines IL-1β 10 ng/mL and TNF-α 10 ng/mL." (PMID 36611893, 2022). "Our study has also revealed that after infection of RPE cells with parasites, mRNA expression of GM-CSF, IL-1β, IL-6 and IL-8 showed a statistical increase." (PMID 36171756, 2022). "The ex vivo infection of SFTSV in PBMCs from healthy donors demonstrated significantly high expression levels of IL-6, IL-1β, and IL-10 induced from clade IV in either PBMCs or supernatants that were tested at 24 h after inoculation." (PMID 35603493, 2022). "Dietary inclusion of Moringa oleifera induced significantly differential modulations of the relative mRNA expression levels of proinflammatory cytokines such as IL-1β, IL-8, and IFN-γ between normal health and infection conditions." (PMID 35812877, 2022). "The protein levels of IL-1β, IL-6, and IFN-β were highest after infection of 12 h, but TNF-α was maintained in the higher levels after 24 h." (PMID 35458442, 2022). "Probing for SARS-CoV2, we see significant increases with infection of SARS-CoV-2, which is similar to the results from combination with IL-6 and IL-1β (ILs)." (PMID 34669512, 2022). "The combined treatment of neurons with IL-1β and IFN-β followed by WNV infection, leads to almost complete control of WNV and the induction of ISGs is detected; meanwhile, sole treatment either with IL-1β, or IFN-β provides only partial control over infection." (PMID 36016430, 2022). "DDIT4 knockout markedly suppressed E. coli-induced pro-inflammatory IL-1β and TNF-α expression, as well as infection-induced NF-κB p65 phosphorylation and nuclear translocation." (PMID 34985734, 2022). "We found the levels of CXCL1, IL-6, IL-1β, CCL3 and CCL4 were higher in the kidney homogenates of female mice infected with the eng1 strain at days 1 and 4 post-infection in comparison to that infected with the ENG1 strain." (PMID 34995333, 2022). "From the present investigation, we found the expression of IL-1β, CXCL10/IP-10 and CCL3/MIP-α increased in the blood and most organs day by day as the infection progressed." (PMID 35584087, 2022).
infection (continued). "After 2 h of infection, the transcriptional upstream regulators EGFR, EGR1, FOXL2, FOXO3, IL1A, IL1B and RELA were activated in MKN-28 cells infected with either H. pylori wt or the ΔhtrA mutant, while WWTR1 was inhibited." (PMID 37193047, 2022). "In the case of severe inflammation or infection, M1 macrophages release TNF-α, IL-1β, IL-12, and IL-23 to participate in the immune response to stimuli." (PMID 36362965, 2022). "Cells were harvested at 10 hr after infection, and the mRNA levels of IL8, IL6, and IL1β were measured by qRT-PCR." (PMID 35762728, 2022). "In F. novicida infections, infected host cells exhibit robust inflammasome activation and IL-1β secretion compared with F. holarctica LVS and F. tularensis Schu S4 infections." (PMID 36389167, 2022). "For both strains of Coxiella, there was little secretion of tumor necrosis factor alpha (TNF-α), IL-1β, and IFN-γ, which have been shown previously to control infection." (PMID 35913176, 2022). "At 24 h post infection, there was increased expression of TNF-α, IL-1β, IL-6, and IL-12 in the lungs of mice infected with the ΔEfb strain compared to those infected with the Newman and ΔEfb + Flag − Efb strains." (PMID 36123338, 2022). "The data show that IL-1β maturation as well as caspase 1 cleavage is abrogated in the NLRP3 knockdown PAMs, suggesting that inflammasome activation induced by ASFV-H240R infection depends on NLRP3." (PMID 36326277, 2022). "In conclusion, our mucosal vaccine candidate Ad-F+Ad-IL-1β elicits stronger mucosal immune responses and a more effective protection against RSV infection than natural immunity generated by a previous infection." (PMID 36003372, 2022). "We extended the analysis to a large panel of soluble factors identifying other cytokines/chemokines upregulated (IP-10, IL-1ra, MCP-1) or downregulated (IL-9, IL-1β, RANTES, MIP-1β) at the earliest stage of infection in household contacts with a positive swab." (PMID 35967321, 2022). "It was shown that Ad5 infection of THP-1 macrophages resulted in increased secretion of cleaved caspase-1 and IL-1β." (PMID 36298668, 2022). "Filaggrin, HIF-1α, VEGF, RANTES/CCL5, IL-17A, IL-1β, MIP-1α and MIP-1β/CCL5 levels were higher during and after infection." (PMID 36482106, 2022). "Repeating mouse infection experiments at 4 hr with the D39 S. pneumoniae strain demonstrated similar BALF cytokine results, with increased TNF and reduced IL‐1β levels for mice infected with D39Δply compared to D39 or the ply complemented strain." (PMID 35835695, 2022). "The differences in IL-1β levels and cell death between wild-type Mtb and the ΔpknF mutant were abolished in TRIF/Myd88-/- BMDMs following ΔpknF mutant infection." (PMID 34324582, 2021). "It has been reported that ASFV can induce IL-1β and TNF-α production in pigs with the increased inflammatory cytokines detected in the serum as early as 7 days post infection (dpi)." (PMID 34310655, 2021). "Levels of G-CSF, IL-1β, IL-5, and IL-6, and chemoattractant VEGF were significantly altered during the acute phase of infection with concomitant detection of bacterial loads in the blood." (PMID 34451491, 2021). "When infection, injury, or inflammation increases in severity, polarization initially adopts the M1 conformation, leading to a systemic influx of TNF-α, IL1β, IL-12, and IL-23 to reconcile homeostasis." (PMID 34831416, 2021). "We observed an increase of the concentration of IL-1β, TNF-α and MPO during the progression of the infection, which positively correlated with the concentration of PTX3 (P < 0.0001, P = 0.0018, P = 0.0139, respectively)." (PMID 34093560, 2021). "Possibly, the increase in IL-1β mRNA levels induced by IRF-3 expression is mediated indirectly and only upon infection with a cytoplasmic DNA virus VACV, as suggested by the modest stimulatory effects of WR-Luc." (PMID 34696416, 2021).
infection (continued). "To do so, we incubated column-purified monocytes isolated from healthy donors with SARS-CoV-2 USA-WA1/2020 at different multiplicities of infection (MOI) and measured IL-1β in supernatants after 24 h as a result of inflammasome activation." (PMID 35095880, 2021). "Next, we detected the expression of IL-6, IL-1β and TNF-α in RAW264.7 cells after infection with the WT or ΔCRISPR strains." (PMID 34727007, 2021). "Infection with the als3Δ/Δ and ece1Δ/Δ single mutants induced significantly less secretion of CXCL8/IL-8, CCL20, IL-1α, and IL-1β than the wild-type parent strain." (PMID 33471869, 2021). "Both IL-1β and TNF-α can be secreted by macrophages in response to viral infections in the infection site." (PMID 34578465, 2021). "In vivo studies with HSV-1 and WNV demonstrate the significance of specific cytokines (IFNγ and IL-1β, respectively) that modulate NSC responses during infection, and provide a crucial model for understanding the complexity of viral pathogenesis in the brain." (PMID 34452333, 2021). "During the acute phase of infection, proinflammatory cytokines (TNF-α, IL-1β, and IL-8) promote the development of effector T cells to fight off the infection." (PMID 33717081, 2021). "The IL-1β and IL-18 expression levels in the HPI+ group were significantly different from those in the control and HPI− groups at 6 and 9 h post-infection (P < 0.01)." (PMID 33678162, 2021). "Burned mice infected with P. aeruginosa M2 showed increased circulating proinflammatory cytokines (IL-6, IL-1β, TNF-α, and IFN-γ) and a rise in anti-inflammatory IL-10 late during infection once clinical symptoms were observed." (PMID 34152806, 2021). "The results showed that most inflammatory factors, including IL-1β, IL-6, IL-8, and TNF-α, were significantly increased after infection." (PMID 34593766, 2021). "Experimental evidence shows ADE, a common factor in secondary infection or prior exposure to DENV infection, induces IL-1β synthesis." (PMID 34447698, 2021). "IL-1β, IL-6, IL-8, MCP-1 and IFNγ, were previously reported to be elevated in lethal infection using a high dose of B. pseudomallei 1026b in AGMs." (PMID 33571211, 2021). "Pro-inflammatory cytokines IL-2, TNF-α, IL-17α, IFN-γ, IL-1β, and MIP-3α are significantly elevated in infection-naïve CF mice (p < 0.050)." (PMID 34475490, 2021). "During infection, activated macrophages secrete proinflammatory cytokines (e.g., TNF-α, IL-1β and IL-6) and inflammatory mediators (e.g., NO and PGE2) to regulate inflammatory responses against pathogens." (PMID 34564598, 2021). "Thus, although inflammasome activation is absolutely required for IL-1β production and anti-Candida host defenses, significant amounts of IL-1β can still be produced in Gsdmd-/- mice to maintain host defenses against C. albicans, alleviating infection in these mice." (PMID 34795266, 2021). "In the spleen, the mRNA levels of IL-1β and TGF-β in the infection group at 7 and 14 dpi were obviously higher than those in the negative control group (P < 0.01)." (PMID 33647718, 2021). "T-helper cell (Th1)-type cytokines, such as TNF-α, IL-6 and IL-1β, and Th2-type cytokines, such as IL-10 and IL-4, were differentially expressed in M. fortis and BALB/c mice in the early stage of infection." (PMID 34689797, 2021). "We showed that infection occurred in HSF cells and increased gene expression and protein secretion of two major proinflammatory CCL-2 and IL-1β markers." (PMID 33737658, 2021). "Since DENV-2 and DENV-4 are from the same ancestor, it is possible that the M, NS2A/B from DENV-4 can increase IL-1β, and NS5 can increase IL-8 in DHF/DSS, when majority of the samples are from primary infection." (PMID 34447698, 2021). "In adult Xenopus, FV3 infection also induces a rapid response (as early as 1dpi) of type I IFN and Mx1 and 2, as well as pro-inflammatory and inflammatory-related genes (IFNγ, IL-1β, and TNF-α) in the kidney." (PMID 34675918, 2021).